MYD88 (MYD88 innate immune signal transduction adaptor)
Diseases named in the same sentence as MYD88 in open-access papers (continued):
Sharing a sentence is not in itself a finding about the gene and the disease.
breast cancer (continued). "As we show in glioblastoma, IL-1β initiates a cascade of events similar to that in aggressive luminal-type breast cancer cell where mRNA and protein levels of MyD88 induce and activate NFĸB, which in turn activates IL-6 for activation of Calcineurin." (PMID 40725140, 2025). "Myeloid differentiation factor 88 (MYD88) plays a critical role in breast cancer through diverse functions." (PMID 40714319, 2025). "Relevant research found that the MyD88 inhibitor TJ-M2010–2 significantly inhibited the proliferation, migration, and invasion of breast cancer cells in vitro." (PMID 41488647, 2025). "Within the scope of this research, we conducted an inquiry into the relationship between MyD88 expression levels and the clinical manifestations of breast cancer." (PMID 39744584, 2025). "Our findings highlight MyD88 as a promising candidate for personalized medicine approaches in breast cancer, warranting further investigation into its mechanistic role and therapeutic potential." (PMID 39744584, 2025). "Through the application of immunohistochemistry (IHC), we validate the clinical relevance of MyD88 expression levels in breast cancer tissues, correlating elevated expression with better patient prognoses." (PMID 39744584, 2025). "In our research, we explored the expression profiles and clinical relevance of MyD88 in breast cancer, revealing its complex contributions to the disease's advancement." (PMID 39744584, 2025). "Within the TME, TLR4 recognizes HMGB1 to activate the MyD88/NF-κB pathway, enhancing breast cancer invasion and angiogenesis." (PMID 41488647, 2025). "This study aims to dissect the intricate relationship between MyD88 expression and its implications in the clinicopathological characteristics and prognostic outcomes of breast cancer." (PMID 39744584, 2025). "This integrative study combines bulk RNA sequencing (RNA-seq), single-cell RNA sequencing (scRNA-seq), and immunohistochemistry (IHC) to explore the prognostic significance and immunological implications of MyD88 in breast cancer." (PMID 39744584, 2025). "To validate our findings, we performed IHC on 100 breast cancer patients, confirming that MyD88 primarily expressed in epithelial cells, with a diffuse cytoplasmic distribution." (PMID 39744584, 2025). "Commencing with a stratification of breast cancer patients by their molecular subtypes, we discerned a pronounced elevation in MyD88 expression within the basal and normal-like subtypes when juxtaposed with the Luminal A, Luminal B, and HER2-enriched subtypes." (PMID 39744584, 2025). "Our study, while contingent upon digital databases and clinical samples that warrant further validation through experimental assays both in vitro and in vivo, establishes MyD88 as a critical component in the etiology of breast cancer." (PMID 39744584, 2025). "In conclusion, MyD88 plays a pivotal role in regulating breast cancer cell proliferation through the activation of multiple key signaling pathways." (PMID 38347830, 2024). "In this review, we provide a comprehensive overview of MyD88’s roles in tumorigenesis, metastasis, drug resistance, the tumor microenvironment, and prognosis in breast cancer." (PMID 38347830, 2024). "MyD88 assumes multifaceted, pivotal roles in the landscape of breast cancer, influencing diverse aspects such as tumor development, drug resistance, stem cell properties, and the intricacies of the immune microenvironment." (PMID 38347830, 2024). "MyD88 plays a central role in breast cancer, exerting a multitude of effects that carry substantial implications." (PMID 38347830, 2024). "Nonetheless, there exists a need for further research to unveil the precise workings of MyD88 and translate its applications into clinical practice, with the ultimate aim of achieving more precise and personalized approaches to managing breast cancer." (PMID 38347830, 2024).
breast cancer (continued). "While normal breast tissues typically maintain low MyD88 expression levels for physiological functions, breast cancer often exhibits significant upregulation." (PMID 38347830, 2024). "Both TLR4 and MyD88 protein expressions are positively correlated with breast cancer cell metastasis." (PMID 38347830, 2024). "The influence of MyD88 on the tumor immune microenvironment is of great significance in the context of breast cancer progression." (PMID 38347830, 2024). "The MyD88-regulated PI3K/Akt pathway appeared to mediate paclitaxel resistance in breast cancer cells by modulating Bax/Bcl-2 expression." (PMID 38347830, 2024). "Studies indicate that adjacent normal tissues and benign breast tumors have lower MyD88 expression, whereas breast cancer demonstrates heightened and pronounced expression." (PMID 38347830, 2024). "By modulating signaling pathways governing the maintenance and functionality of breast cancer stem cells (BCSCs), MyD88 regulates tumor initiation, progression, recurrence, and therapy resistance." (PMID 38347830, 2024). "By delving deeper into the multifaceted impacts of MyD88 in breast cancer, we anticipate the emergence of novel strategies for the treatment and management of this disease." (PMID 38347830, 2024). "In conclusion, MyD88 plays a significant role in regulating breast cancer stem cell characteristics and functions." (PMID 38347830, 2024). "Inhibiting MyD88 leads to decreased clonogenicity, and MyD88 shRNAs result in negative selection in the development of in vivo xenograft tumors derived from ERneg breast cancer cells." (PMID 38347830, 2024). "Currently, MyD88 is regarded as a critical signaling molecule with diverse roles in the development and progression of breast cancer." (PMID 38347830, 2024). "In breast cancer, MyD88 is recognized as a key regulator with a significant impact on cell proliferation." (PMID 38347830, 2024). "Understanding the expression patterns of MyD88 contributes to a better comprehension of its roles in breast cancer initiation, progression, and treatment." (PMID 38347830, 2024). "In breast cancer, MyD88 knockdown reduces the proliferation and migration of MCF-7 cells and increases the sensitivity of MCF-7 cells to paclitaxel." (PMID 38785969, 2024). "The assessment of MyD88 expression levels offers a means to comprehensively gauge breast cancer invasiveness and predict patient prognosis, thereby establishing a foundation for informed decisions in personalized treatment." (PMID 38347830, 2024). "Engaging in various signaling pathways, MyD88 influences proliferation, migration, and invasion of breast cancer cells." (PMID 38347830, 2024). "Through modulation of inflammatory responses and immune reactions, MyD88 impacts the immune microenvironment of breast cancer." (PMID 38347830, 2024). "The expression of the MyD88 gene in breast cancer tissues is higher compared to adjacent normal tissues and benign tumors." (PMID 38347830, 2024). "In breast cancer, the expression of MyD88 varies within breast cancer cells, tumor tissues, and the surrounding microenvironment." (PMID 38347830, 2024). "Against this backdrop, Myeloid Differentiation Factor 88 (MyD88) assumes a crucial role in breast cancer." (PMID 38347830, 2024). "MyD88 exerts influence over several critical aspects of breast cancer, including metastasis, recurrence, drug resistance, and the regulation of cancer stem cell properties." (PMID 38347830, 2024). "TJ-M2010-2 affects the MyD88/GSK-3β and MyD88/NF-κB signaling pathways and inhibits the proliferation, migration, and invasion of breast cancer cells." (PMID 38785969, 2024). "In particular, it was observed that the expression levels of TLR4 and MyD88 are related to the metastatic and invasive potential of the breast cancer cell type." (PMID 37822929, 2023).
breast cancer (continued). "In this regard, previous studies have reported suppression of LPS-induced migration and invasion of breast cancer cells after targeting MyD88-dependent signaling pathways, for instance, MyD88/GSK-3β/Snail and MyD88/NF-κB/Snail." (PMID 37749630, 2023). "The data supported the oncogenic role of MYD88 in glioma, consistent with the findings in colorectal cancer and breast cancer." (PMID 37456890, 2023). "Studies in humans have shown that MyD88 mediates colorectal cancer cell proliferation, migration and invasion via NF-κB/AP-1 signaling pathway and TLR4/MyD88 signaling determines the metastatic potential of breast cancer cells." (PMID 36476317, 2022). "Since the MyD88−/− mice had a C57Bl/6 background, we further worked with the C57Bl/6 murine breast cancer cell line E0771-LG for our in vivo experiments." (PMID 36224342, 2022). "Astragalus polysaccharides, a kind of traditional Chinese medicine, can modulate macrophages through TLR4/MyD88 signaling to enhance the immune response in breast cancer patients." (PMID 34141706, 2021). "For example, the interaction of LMW-HA with CD44 and TLR enhanced the production of IL-1β/IL-8 via the subsequent activation of MyD88/NF-κB and finally promoted the invasiveness of breast cancer cells." (PMID 33986244, 2021). "In previous research, we have found that TLR4 was linked to the metastasis of breast cancer in vitro and in vivo by activating the TLR4/MyD88/NF-κB signaling pathway." (PMID 34475958, 2021). "Previous studies have suggested that DMDD shows significant antitumor potential against human breast cancer by inhibiting the TLR4/MyD88/NF-κB and MAPK pathway in vitro and in vivo." (PMID 33613291, 2021). "TLR4/MyD88 pathway has been found to be upregulated in breast cancer cell line with high invasion rate as compared to the breast cancer cell line with lower invasion rate." (PMID 34671606, 2021). "MiR-155-3p can also act as a tumor suppressor and reverse PTX resistance via the negative regulation of MYD88 in human breast cancer." (PMID 33612481, 2021). "Overall, this study provides first comprehensive evidence on the involvement of canonical signaling of TLR3 using MyD88–cyclin D1-mediated breast cancer cell proliferation." (PMID 33072559, 2020). "Results had revealed that TLR3 ligand treatment significantly enhanced breast cancer cell proliferation marked by an upregulated expression of cyclinD1, but the same was suppressed by the addition of MyD88 inhibitor." (PMID 33072559, 2020). "In this present study, we had reported the mechanistic pathway of TLR3 ligand-induced breast cancer cell proliferation through MyD88-mediated gateway." (PMID 33072559, 2020). "In the present study, we found that the expression of TLR4, MyD88, p-NF-κB p65, p-IκBα and p-IKKα/β in breast cancer cells was significantly down-regulated after AT-I treatment." (PMID 33363472, 2020). "Our previous work demonstrated that the expression of MyD88 was increased in breast cancer tissues, and its expression level was correlated with PTX resistance." (PMID 31259152, 2019). "As expected, we concluded that MyD88 serves as a target of miR-149-5p in breast cancer 231/PTX cells, and the luciferase reporter gene experiments showed that miR-149-5p directly targeted the 3′UTR of MyD88." (PMID 31259152, 2019). "In particular, MyD88 is required for nerve injury induced upregulation of CCL2, in DRG neurons, consistent with another report in which the release of CCL2 was dependent on MyD88 pathway in murine mammary carcinomas cells." (PMID 27312666, 2016). "This study evaluated the prognosis of breast cancer patients based on contributors to the innate immune response: myeloid differentiation primary response 88 (MyD88) and Toll-like receptor 4 (TLR4)." (PMID 25360699, 2014). "We concluded that TLR4/MyD88 signaling contributed to their invasive activity of human breast cancer cells via autocrine and/or paracrine which played an active role in human breast cancer metastasis." (PMID 25299052, 2014).
breast cancer (continued). "We measured the production of MyD88 and cytokine expression capacity of human breast cancer response to LPS." (PMID 25299052, 2014). "LPS triggered increased expression of TLR4 downstream signaling pathway protein myeloid differentiation factor 88(MyD88) and resulted in interleukin (IL)-6 and IL-10 higher production by human breast cancer cells." (PMID 25299052, 2014). "MyD88 homodimerization inhibitory peptide also led to decreased growth in four different murine mammary carcinomas as well as in the human breast cancer cell line providing evidence that MyD88 is important for growth and metastasis of breast cancer." (PMID 23305364, 2012). "Furthermore, in breast cancer patients, MyD88 emerged as a noteworthy independent prognostic predictor, as evidenced by multivariate Cox regression analysis." (PMID 39744584, 2025). "MyD88, a key adaptor protein in breast cancer, holds immense clinical potential." (PMID 39744584, 2025). "Moreover, the interaction of MyD88 with immune checkpoint therapy plays a pivotal role, significantly impacting breast cancer treatment outcomes." (PMID 38347830, 2024). "Furthermore, MyD88’s protein expression level exhibits a positive correlation with axillary lymph node metastasis and histological grade, while the co-expression of TLR4 and MyD88 is positively correlated with breast cancer cell metastasis." (PMID 38347830, 2024). "Notably, the expression levels of TLR4 and its downstream adaptor protein MyD88 are significantly elevated in breast cancer compared to adjacent normal tissue, and the upregulation is associated with a poor prognosis." (PMID 38725852, 2024). "MyD88 assumes a pivotal role in the clinical evaluation and prognosis of breast cancer." (PMID 38347830, 2024). "In addition, the TLR2/MyD88 signaling pathway can activate the NF-κB and Wnt signaling pathways, ultimately inducing the proliferation of colorectal and breast cancer cells." (PMID 38785969, 2024). "The MyD88 pathway also mediates immune responses that impact breast cancer progression." (PMID 38347830, 2024). "However, further research is needed to gain deeper insights into the regulatory mechanisms of MyD88 in breast cancer cell proliferation, with the goal of developing more precise and effective treatment strategies." (PMID 38347830, 2024). "MyD88 also plays a critical role in breast cancer metastasis." (PMID 38347830, 2024). "In summary, MyD88 expression in breast cancer exhibits variability." (PMID 38347830, 2024). "In conclusion, MyD88 promotes cancer cell migration, invasion, and the establishment of secondary tumors in distant organs through diverse pathways, significantly impacting breast cancer metastasis." (PMID 38347830, 2024). "This highlights MyD88 as a significant potential therapeutic target, and inhibiting its function may contribute to restraining the growth and dissemination of breast cancer cells." (PMID 38347830, 2024). "Similarly, the MyD88 inhibitor TJ-M2010-2 suppresses the proliferation, migration, and invasion of breast cancer cells by intervening in the MyD88/GSK-3β and MyD88/NF-κB signaling pathways." (PMID 38347830, 2024). "A comprehensive understanding of the mechanisms underpinning MyD88’s actions in breast cancer not only unravels the molecular complexities governing tumor progression but also unveils fresh perspectives and potential targets for shaping breast cancer treatment strategies." (PMID 38347830, 2024). "A comprehensive comprehension of the role of MyD88 in shaping the tumor microenvironment greatly enhances our understanding of breast cancer development mechanisms, and it offers a strong theoretical foundation for the development of innovative therapeutic strategies." (PMID 38347830, 2024). "Elevated MyD88 expression is correlated with larger tumor size, lymph node metastasis, and higher histological grades, suggesting MyD88’s potential as a biomarker for appraising breast cancer’s invasiveness and progression." (PMID 38347830, 2024).
breast cancer (continued). "Furthermore, the MyD88/NF-κB signaling pathway plays a central role in drug resistance in breast cancer." (PMID 38347830, 2024). "Additionally, glycation has been linked to activating the RAGE/TLR4/MyD88 signaling pathway and upregulating MMP9 expression in breast cancer, thus increasing migration and invasion." (PMID 37174618, 2023). "SP1-induced upregulation of MyD88 contributes to the chemoresistance of breast cancer." (PMID 34307888, 2021). "It was also suggested that TLR4/MyD88 levels could serves as a useful prognostic biomarker for breast cancer patients." (PMID 34671606, 2021). "Likewise, AGAP2-AS1 promotes cell growth and inhibits apoptosis in breast cancer (BC) by inducing the histone acetylation in the MYD88 promoter region." (PMID 34461912, 2021). "Based on this scenario, overexpression of NLRP3/MyD88 and cytokines during hyperglycemia in breast cancer cells and cardiomyocytes could be a key player in cardiotoxicity and resistance to ipilimumab." (PMID 33096896, 2020). "This response is hypothesized to be via the MyD88 gateway that culminates in the proliferation of breast cancer cells." (PMID 33072559, 2020). "Our work indicates that UA could reverse PTX resistance in breast cancer by modulating miR-149-5p and MyD88 expression, which sheds light on the improvement of breast cancer chemotherapy and provides evidence for further clinical investigation." (PMID 31259152, 2019). "Thus, our data indicate that UA can reverse PTX resistance by targeting the miRNA-149-5p/MyD88 axis in breast cancer cells." (PMID 31259152, 2019). "To explore whether UA reversed PTX resistance by targeting MyD88 in breast cancer, we evaluated the effect of UA on the expression of MyD88." (PMID 31259152, 2019). "UA reverses PTX resistance through the upregulation of MyD88 expression in breast cancer cells." (PMID 31259152, 2019). "Interestingly, LPS treatment did not result in an increased nuclear translocation of NF-κB in MDA-MB-435-Hyg breast cancer cells despite Myd88 and TRAF6 expression." (PMID 26863029, 2016). "The activation of TLRs expressed on breast cancer cells may result in profound consequences for tumor growth through MyD88." (PMID 25360699, 2014). "It is unknown which pathway plays the most important role in breast cancer, and little is known about the expression of MyD88 in breast cancer and its correlation with TLR4 in tumor prognosis." (PMID 25360699, 2014). "The role of TLR/MyD88 pathway activation in breast cancer has been controversial." (PMID 25360699, 2014). "Furthermore, little is known about the expression of MyD88 in breast cancer or its correlation with tumor development." (PMID 25360699, 2014). "Thus, we assessed the expression of MyD88 and TLR4 in 205 breast cancer patients and confirmed that MyD88 and TLR4 expression was correlated with poor DFS and OS." (PMID 25360699, 2014). "However, it remains unclear whether MYD88 influences the progression of breast cancer through m6A or PCD." (PMID 41357233, 2025). "However, it is noteworthy that in some cases of breast cancer, miR-155 can act as a tumor suppressor, counteracting paclitaxel resistance through the downregulation of myeloid differentiation primary response gene 88 (MYD88)." (PMID 41463125, 2025). "Therefore, it is plausible that through its significant positive correlation with M1 macrophages, MYD88 may modulate the functional state of M1 macrophages, thereby influencing the progression of breast cancer." (PMID 41357233, 2025). "Furthermore, MyD88 can affect breast cancer proliferation through the PI3K/AKT signaling pathway." (PMID 38347830, 2024). "Differential MyD88 expression may also exist among distinct molecular subtypes of breast cancer." (PMID 38347830, 2024). "However, it remains unclear whether miR-149 can regulate PTX resistance in breast cancer by regulating MyD88 transcriptional activity." (PMID 31259152, 2019).